SLC25A48 (solute carrier family 25 member 48)
Description:
Mitochondrial transporter that mediates choline import across the inner mitochondrial membrane, thereby regulating mitochondrial choline levels and downstream metabolism, including betaine and purine nucleotide synthesis. Plays a key role in mitochondrial respiration, brown fat thermogenesis, and the maintenance of mitochondrial membrane integrity (By similarity).
Synonyms: FLJ44862
Tractability: Antibody: UniProt predicts a signal peptide or a membrane-spanning region.
Gene: Protein-coding gene on chromosome 5 (135,476,913 to 135,889,770, forward strand). Ensembl gene ENSG00000145832.
Subcellular location: Mitochondrion membrane; Mitochondrion inner membrane
Subcellular location (Human Protein Atlas): Intermediate filaments; Actin filaments
Gene Ontology:
Molecular function: choline transmembrane transporter activity; protein binding
Biological process: choline transport; transmembrane transport
Cellular component: mitochondrial inner membrane; mitochondrial membrane; mitochondrion
Genetic constraint (gnomAD): Loss-of-function variants: 29 observed, 32.78 expected, observed/expected ratio (o/e) 0.88, 90% interval 0.66 to 1.21. The upper end of that interval is the gene's LOEUF score, 1.21, which puts it in group 5 of 6, group 1 being the genes least tolerant of losing a copy. Missense variants: 396 observed, 429.02 expected, observed/expected ratio (o/e) 0.92, 90% interval 0.85 to 1. Synonymous variants: 162 observed, 176.39 expected, observed/expected ratio (o/e) 0.92, 90% interval 0.81 to 1.05.
Homologues: Orthologues: chimpanzee SLC25A48 (98% identical), pig SLC25A48 (91% identical), macaque SLC25A48 (88% identical), guinea pig SLC25A48 (87% identical), mouse Slc25a48 (85% identical), rat Slc25a48 (85% identical), dog SLC25A48 (81% identical), rabbit SLC25A48 (69% identical), tropical clawed frog slc25a48 (64% identical), zebrafish slc25a48 (61% identical). Paralogues in human: SLC25A45 (45% identical), SLC25A47 (40% identical), SLC25A29 (36% identical), SLC25A20 (33% identical), SLC25A12 (30% identical), SLC25A13 (29% identical), SLC25A15 (27% identical), SLC25A21 (27% identical), SLC25A22 (27% identical), SLC25A2 (26% identical), SLC25A34 (26% identical), SLC25A19 (25% identical), and 37 more.
Diseases named in the same sentence as SLC25A48 in open-access papers:
SLC25A48 is named in the same sentence as 10 diseases in open-access papers, as found by Europe PMC text mining. Sharing a sentence is not in itself a finding about the gene and the disease. The quoted sentences say what the papers report.
lung carcinoma (1 paper, 2024). "Within 24 h post induction of SLC25A48 depletion, we found over 50% of ovarian and lung cancer cells died, and 20% of pancreatic cancer cells were dead." (PMID 39111307, 2024).
non-small cell lung carcinoma (1 paper, 2024). A group of at least three distinct histological types of lung cancer, including non-small cell squamous cell carcinoma, adenocarcinoma, and large cell carcinoma. "Here, we used four independent human cancer cells, ovarian cancer cells (SKOV3), pancreas adenocarcinoma (PA-TU-8988T), and non-small-cell lung cancer cell lines (A549 and H1299), that expressed SLC25A48." (PMID 39111307, 2024).
Obesity (1 paper, 2023). Accumulation of substantial excess body fat. "The top two loci with the strongest association signals identified by sfkit were co-located with SLC25A48 and FTO genes, recapitulating previously reported genetic factors of obesity." (PMID 37246709, 2023).
osteosarcoma (1 paper, 2024). A usually aggressive malignant bone-forming mesenchymal neoplasm, predominantly affecting adolescents and young adults. "Similarly, the depletion of SLC25A48 in U2OS osteosarcoma cells impaired the cell cycle in the transition from the G1-to-S phase." (PMID 39111307, 2024).
ovarian carcinoma (1 paper, 2024). A malignant neoplasm originating from the surface ovarian epithelium. "In agreement with the finding in SNP-KI cells, ovarian cancer cells lacking SLC25A48 failed to initiate the G1-to-S phase transition." (PMID 39111307, 2024).
cancer (2 papers, 2022 to 2024). A tumor composed of atypical neoplastic, often pleomorphic cells that invade other tissues. "Second, while SLC25A48 loss in cancer cells resulted in impaired cell growth, supplementation with the downstream product betaine was insufficient to rescue cell growth." (PMID 39111307, 2024). "In all cancer cells tested, genetic loss of SLC25A48 by the CRISPR-Cas9 system resulted in a significant reduction in cell viability." (PMID 39111307, 2024). "Given the critical role of de novo purine nucleotide synthesis in cancer, we next asked if SLC25A48-mediated changes in cell proliferation extended to cancer cells." (PMID 39111307, 2024). "How the SLC25A48-mediated choline catabolic pathway is regulated in pathophysiology, including cancer and metabolic disorders, is an important area of future research." (PMID 39111307, 2024). "Notably, human cells carrying a single nucleotide polymorphism on the SLC25A48 gene and cancer cells lacking SLC25A48 exhibited decreased mitochondrial choline import, increased oxidative stress, and impaired cell proliferation." (PMID 39111307, 2024). "Their RNA expression levels (lacking SLC25A48) across cancers were surveyed in ONCOMINE." (PMID 35288533, 2022).
SLC25A48 also shares sentences with these, for which no sentence is quoted: glioma (1 paper); metabolic disorders (1); pancreas adenocarcinoma (1); pancreatic cancer (1).